CRP (C-reactive protein)
Diseases named in the same sentence as CRP in open-access papers (continued):
Sharing a sentence is not in itself a finding about the gene and the disease.
depression (continued). "In a study of patients with metastatic lung cancer, depression partially mediated the relationship between systemic inflammation, measured by C-reactive protein levels, and reduced survival." (PMID 41409248, 2025). "Individuals with PTSD and depression frequently show elevated levels of pro-inflammatory markers, such as interleukin-6 (IL-6) and C-reactive protein (CRP)." (PMID 41347040, 2025). "Male sex, smoking, dyslipidemia, depression, uveitis, cardiac involvement, elevated CRP, ASDAS-CRP, BASDAI, and ASQoL scores, cervical BASRI score, and NSAID and csDMARD use were significantly associated with higher oxidative stress levels." (PMID 41227142, 2025). "Other findings of our study were the correlations between declining cognitive status and depression, low serum albumin, and high serum CRP, confirming the results of previous studies." (PMID 40565866, 2025). "The reduced likelihood of remission is due to an increased number of tender joints, higher general health and pain scores and slightly elevated ESR and CRP levels in patients with a possible depression or anxiety disorder." (PMID 39504461, 2025). "It was determined that CRP partially mediated the relationship between dietary inflammation and depression and anxiety." (PMID 40110388, 2025). "A thorough meta-analysis established a clear link between increased concentrations of IL-6 and CRP and the presence of major depressive disorder." (PMID 40363978, 2025). "Studies have shown that depression is linked to elevated levels of pro-inflammatory cytokines such as IL-6, TNF-α, and CRP." (PMID 40697716, 2025). "There was a weak positive Pearson correlation (R = 0.29) between depression in the EA group and CRP." (PMID 40837576, 2025). "There are two high levels of inflammatory substances in depression: IL-6 and C-reactive protein (CRP)." (PMID 41409784, 2025). "Future intervention and prevention efforts should thus account for these complex interrelations between ACEs, as well as their apparent differential effects on CRP and depressive symptoms, when aiming to improve depression-related outcomes." (PMID 40357904, 2025). "A third of patients with depression do not respond to conventional treatment with antidepressant drugs, and a third of patients suffering from depression have elevated serum C-reactive protein levels (CRP > 3 mg/L) as a marker of inflammation." (PMID 40699818, 2025). "The results for anthropometric variables, body composition, V̇O2peak, Ki67, IL‐6, CRP protein, and depression from T1 to T2 are shown in." (PMID 40859620, 2025). "In the female group, the highest interaction intensities (%) for depression were observed with IL-6, hsCRP, CRP, vitamin D, and D-dimer." (PMID 40563433, 2025). "Increased CRP levels have been related to more depression symptoms, especially among persons facing high social stressors or strains, implying a potentially synergistic impact between this proinflammatory marker and social strain on future MDD severity." (PMID 40686933, 2025). "Previous studies on symptom clusters of depression focused on high-sensitivity C-reactive protein (hsCRP) and few additional biomarkers, whereas studies with more comprehensive immunological phenotyping are lacking." (PMID 39799156, 2025). "Results show that patients with depression had significantly higher increases at 2 years compared to baseline for all investigated parameters (CRP—p = 0.032/Fibrinogen—p = 0.030/Interleukin-6—p < 0.001/TNF-α -p = 0.007/Cortisol—p < 0.001)." (PMID 40363978, 2025). "Analyses have shown that a functional single-nucleotide polymorphism (SNP) in the promoter region of the IL-6 gene leads to elevated values of IL-6 and CRP, which correlate with the severity of depressive syndrome." (PMID 40699818, 2025). "The cytokine model of depression posits that increased fibrinogen and CRP would predict more MDD symptoms over lengthy periods via several plausible pathways." (PMID 40686933, 2025).
depression (continued). "First, chronic stress, often experienced by individuals with depression, can activate the immune system and trigger inflammation, resulting in elevated CRP levels." (PMID 38255209, 2024). "Moreover, several subcortical brain structures and three inflammatory markers—CRP, neutrophils, and leukocytes—significantly mediated the association between frailty and depression, suggesting that both neurobiological and inflammatory mechanisms underlie the frailty-depression relationship." (PMID 38782943, 2024). "A recent meta-analysis encompassing 30 studies reveals that 27% of individuals with depression experience chronic low-grade inflammation (CRP >3 mg/L), while the majority (58%) of patients show CRP levels exceeding 1 mg/L." (PMID 40656087, 2024). "These also include hypertriglyceridemia, an increased homocysteine level, an increase in the Lp(a) value, and increased C-reactive protein (CRP) levels, as well as depression." (PMID 38893019, 2024). "Recurrent UC patients had higher baseline CRP and fecal calprotectin levels, increased anxiety and depression, and more severe fecal incontinence." (PMID 39009899, 2024). "Patients with depression exhibit similar changes associated with immune system activation, such as increased IL-6, TNF-α, and C-reactive protein levels." (PMID 38702637, 2024). "A possible explanation for this difference has to do with the influence of sex hormones, particularly periodic changes in ovarian hormones, which are known to regulate C-reactive protein levels, which in turn affect the state of depression." (PMID 39902244, 2024). "Poor sleep quality or inadequate sleep can worsen depression by disrupting the balance of mood-related neurotransmitters and heightening inflammation, including markers like c-reactive protein and systemic inflammation." (PMID 39606068, 2024). "It was shown that in both treatment-resistant depression and healthy control participants ayahuasca significantly decreased the amount of CRP, and that pretreatment treatment-resistant depression participants started with elevated CRP in their bloodwork." (PMID 38576633, 2024). "In a Mendelian randomisation study, genetically predicted higher levels of IL-6 were related to increased depressive symptoms, whereas genetic instruments for elevated CRP showed protective effects in depression." (PMID 38699297, 2024). "Blood pressure, blood lipids, blood glucose, and hs-CRP were assessed as physical health outcomes, whereas post-traumatic stress disorder, depression and anxiety symptoms, pain, and quality of life were assessed as mental health outcomes." (PMID 39498167, 2024). "At each visit, all of the DAS28 components (TJC, SJC, ESR, and CRP) were significantly higher among RA patients with depression." (PMID 38610822, 2024). "CRP levels were much higher both in suicide attempters (12.48 ± 28.42) and the depression group (2.98 ± 4.03) vs. (1.41 ± 2.36) in controls (p < 0.001)." (PMID 38737407, 2024). "The patients with severe dissatisfaction with their workplace registered severe depression, and high levels of hs CRP." (PMID 39064476, 2024). "Our previous studies have shown that the expression of C-reactive protein (CRP) is increased in patients with poststroke depression." (PMID 38898454, 2024). "There are also studies that suggest that there is a close relationship between depression and inflammation, considering the fact that CRP levels have been correlated with depression scores at multiple dynamic assessments." (PMID 38610822, 2024). "Several ongoing randomized controlled trials are currently recruiting depressed patients with elevated CRP levels for the study of anti-inflammatory treatments for depression." (PMID 38596631, 2024). "This indicates that participants with higher baseline CRP showed less improvement in depression symptom severity." (PMID 38130122, 2024).
depression (continued). "C-reactive protein (CRP), an acute-phase reactant that reflects inflammation, is associated with depression severity and response to other rapid-acting antidepressants." (PMID 38956594, 2024). "Furthermore, specific single-nucleotide polymorphisms (SNPs) within the CRP gene influence serum CRP levels, with certain hereditary SNPs like the A allele of rs1417938 and the C allele of rs1205 being more common among individuals with a familial predisposition to depression." (PMID 38377025, 2024). "More comprehensive studies are needed in the future to quantify the relationship between CRP and depression." (PMID 38468463, 2024). "Studies of CRP and other individual inflammatory markers have been invaluable in establishing the link between inflammation and depression and have furthered our understanding of the role cytokines play in the development and persistence of depression." (PMID 38442505, 2024). "Studies have shown that depression is often accompanied by elevated levels of pro-inflammatory markers such as C-reactive protein and interleukin-6, which not only lead to the onset and progression of depression but also significantly increase the risk of CVD." (PMID 39450305, 2024). "Polymorphisms in genes such as IL-1β, IL-6, IL-10, TNF, MCP1/CCL2, CRP, and phospholipase A2 are among the most consistently observed findings in major depressive disorder." (PMID 39723161, 2024). "We assessed the prevalence of low-grade inflammation in adults with treatment-resistant depression (TRD) in Pakistan, an LMIC, and investigated associations between peripheral C-reactive protein (CRP) levels and depressive symptoms." (PMID 39359158, 2024). "This association remained significant after controlling for baseline BMI and several other factors, such as depression severity, serum lipid profile and C-reactive protein (CRP)." (PMID 38980569, 2024). "For example, groups with higher depression symptoms demonstrated significantly higher circulating CRP levels in comparison with those with lower depression symptom scores." (PMID 38820411, 2024). "Increased levels of CRP were also observed in a group with depression and trauma, in comparison to healthy pregnant volunteers." (PMID 38820411, 2024). "Inflammatory markers, such as C-reactive protein, tumor necrosis factor-α, and interleukin-6, were elevated in both depression and migraine." (PMID 38881795, 2024). "Patient*innen mit Depression, dann korreliert Fatigue nicht notwendigerweise mit CRP und nur etwa ein Drittel der Patient*innen zeigt eine erhöhte Entzündungsaktivität in Form einer „low-grade inflammation“." (PMID 39325193, 2024). "C-reactive protein, as an indicator of systemic inflammatory response, allows for the identification of potential connections between inflammation and depression in hemodialysis patients." (PMID 38255209, 2024). "Some studies have indicated that elevated levels of C-reactive protein (CRP) and interleukin-6 (IL-6) in diabetic patients are closely related to the worsening of symptoms and increased depression levels in patients with schizophrenia." (PMID 39421064, 2024). "Depression can result in elevated levels of C-reactive protein, interleukin (IL)-1β, IL-6, and tissue necrotic factor-alpha, as well as an increase in the concentration of inflammatory molecules, such as NLRP3 inflammasomes." (PMID 39006364, 2024). "The results of the study showed that SNPs of eNOS, HSP70, FKBP5, miR-146a, ACE2, MAS1, SGK1, IL-4–589, IL-6–174, TNF-α–308, CRP–717, 5-HTTLPR, and BDNF genes are associated with the comorbidity of coronary heart disease and depression." (PMID 38745947, 2024). "It is evidenced by the vulnerable but significant correlation between the onset and development of depression and elevated levels of inflammatory markers such as CRP, TNF-α, IL-6, and IL-1 (Hacimusalar and Eşel, 2017)." (PMID 38384936, 2024).
depression (continued). "Patients with schizophrenia and depression have been reported to exhibit an inverse relationship between blood levels of CRP and thickness of the cerebral cortex." (PMID 37348803, 2024). "Individuals suffering from depression often show elevated levels of pro-inflammatory markers, including interleukins (IL-1β, IL-6), TNFα, and C-reactive protein (CRP)." (PMID 39767653, 2024). "A meta-analysis demonstrated that interleukin-6 (IL-6), C-reactive protein (CRP), and tumor necrosis factor-α (TNF-α) are the inflammatory factors most closely associated with depression." (PMID 38877455, 2024). "We also report associations between single inflammatory proteins and somatic symptoms (IL-6, CRP), fatigue (CRP), and depression severity (IL-6, CRP)." (PMID 38442505, 2024). "Repeated measures of proinflammatory markers (e.g., hs-CRP and IL-6) over time would have provided more insights into the temporal relationship between inflammation and depression." (PMID 37848651, 2024). "For example, a study of outpatients with major depressive disorder reported a strong correlation (r = 0.86) between plasma and cerebrospinal fluid levels of C-reactive protein (CRP), an acute-phase biomarker of inflammation." (PMID 37348803, 2024). "The decrease in CRP correlated with a decrease in the Montgomery-Åsberg Depression Rating Scale (MADRS) scores among those with depression." (PMID 38576633, 2024). "Commonly observed AEs included headache related to surgical procedures, nausea, depression, muscle spasticity, vomiting, increased blood glucose, elevated C-reactive protein levels, constipation, fatigue, pain in extremity, and urinary tract infection." (PMID 39483715, 2024). "The integrated approach, assessing both BDNF and CRP, aims to offer a comprehensive view of the intricate interaction among oxidative stress, inflammatory conditions, and depression in these patients." (PMID 38255209, 2024). "Particularly, studies have shown slightly differing statistical patterns, such as varying correlations between CRP and depression across different genders, with some studies reporting contradictory findings." (PMID 39329797, 2024). "Magnesium deficiency is linked to elevated C-reactive protein (CRP) and its precursors, such as interleukin (IL)-6 and IL-1, which are associated with the prevalence and severity of depression." (PMID 39203767, 2024). "Meanwhile, a study in the Czech Republic with severely obese individuals suggested the possibility of CRP to mediate the relationship between changes in visceral adiposity and the thickness of depression-related cortical areas." (PMID 39064755, 2024). "In the next step, the concentrations of zinc, albumin a, CRP, and IL-6 were compared between the groups of patients with unipolar depression (UD), bipolar depression (BDD), and the group of healthy subjects (HC)." (PMID 38785543, 2024). "Although some findings have found that inflammatory markers (e.g. high sensitivity C-reactive protein, white blood cells) increased with increasing severity of symptoms of depression, this correlation is affected by gender." (PMID 38666135, 2024). "Logistic regression models were built to assess the relationship between pre-treatment CRP (≥ or <3 mg/L) and individual depressive symptoms measured using the Hamilton Depression Rating Scale." (PMID 39359158, 2024). "So, we aimed to evaluate the role of BDNF and CRP in suicidal behavior among Iranian patients with major depressive disorder." (PMID 39039500, 2024). "The inverse correlation was consistent after controlling for baseline depression, as well as CRP and substance use." (PMID 38549611, 2024). "Unhealthy eating habits, which are common in people with depression, can also contribute to elevated CRP levels." (PMID 38255209, 2024).
depression (continued). "While it is challenging to genetically instrument lifestyle factors, we conducted mediation analyses to explore the extent to which smoking cessation, frequency of alcohol intake, body mass index (BMI), and CRP levels mediate the effect of depression on LTL." (PMID 38760657, 2024). "Clinical studies have found a positive correlation between high levels of hs-CRP and the severity of depression at baseline in patients with myocardial infarction." (PMID 38404466, 2024). "Depression and well-being score associations with complement component 3 (CES-D only) c-reactive protein, interleukin 6, leptin, white blood cell counts, neutrophils and the inflammatory biomarker score were observed." (PMID 38560580, 2024). "A widely accepted consensus supports that the increased presence of IL-6, TNF, and C-reactive protein (CRP) in the bloodstream of depressive disorder patients compared to their healthy counterparts." (PMID 38627723, 2024). "Significantly higher levels of peripheral C-reactive protein (CRP) have been found in individuals with suicidal behavior in contrast to participants with depressive disorders as well as healthy individuals." (PMID 38276099, 2024). "A meta-analysis of individuals comparing age, HDL-cholesterol levels, BMI, and more revealed that individuals who scored higher depression levels also had higher CRP levels." (PMID 37754956, 2023). "It was discussed that CRP concentrations play the role of biomarker to differentiate between major depressive disorder and bipolar disorder depression in both depressed and euthymic states in these individuals." (PMID 37873776, 2023). "Persistent elevation of pro-inflammatory markers, such as C-reactive protein (CRP), IL-6, and IL-1 in depression can promote the development and progression of atherosclerosis, a condition characterized by the buildup of fatty plaques in the arterial walls." (PMID 37599890, 2023). "Older adult T2DM patients with depression have significantly elevated levels of C-reactive protein, interleukin-6 and tumor cytokines, which also contribute to frailty." (PMID 38089021, 2023). "Despite non-significance, the observed trend was consistent with previous studies which found that the increased CRP was stronger in male patients with depression compared with female patients." (PMID 36864045, 2023). "In female patients aged 18–44 years, testosterone (Z = 4.292, P < 0.001) and CRP (Z = 5.563, P < 0.001) were higher in manic episodes than in depressive episodes." (PMID 37340368, 2023). "The data from 3 phase 3 RCTs revealed that approximately 40% of patients had remission of depression after 12 weeks of ixekizumab medication, whereas serum levels of C reactive protein improved." (PMID 37240864, 2023). "The relationship between serum magnesium, CRP, and depression in subjects with major depressive disorder needs further examination." (PMID 37049401, 2023). "Addressing this gap, we conducted a short-term longitudinal study examining the link between SMU and C-reactive protein (CRP), a biological marker of systemic inflammation predictive of major depression, chronic diseases, and mortality." (PMID 38064253, 2023). "Miller and coauthors previously presented data showing that poor children show greater levels of depression and anxiety than children with a better economic status, along with blood markers of inflammation like C-reactive protein and cytokines." (PMID 36838809, 2023). "Elevated C-reactive protein (CRP), tumor necrosis factor alpha (TNF-α), and interleukin-6 (IL-6) are the major molecular inflammatory signature associated with depression in general population." (PMID 37365247, 2023). "According to a study, CRP can be used as a differentiative marker between manic and depressive episodes, with significantly higher levels during the manic episode." (PMID 37803327, 2023).